GFRA1 (GDNF family receptor alpha 1)
Diseases named in the same sentence as GFRA1 in open-access papers (continued):
Sharing a sentence is not in itself a finding about the gene and the disease.
tumor (33 papers, 1999 to 2026). "Successful retargeting has been demonstrated against a range of tumor-associated receptors, including IL13Rα2, uPAR, GFRα1, HER2, EGFR, PSMA, and EGFRvIII, enabling selective infection of various cancer cell types." (PMID 41403403, 2026). "In summary, GFRA1 epigenetic modification sequences in TSS associated with tumor invasion and poor prognosis." (PMID 33175846, 2020). "Next, we investigated for any potential association of tumor expression of mRNA or protein for GFRα1, GFRα3 and SDC3 with the clinicopathologic features of MC." (PMID 23351331, 2013). "Expression of GFRα1 mRNA was significantly associated with younger patient age (P = 0.005), tumor lymph node metastasis (LNM) (P = 0.013), higher clinical stage (P = 0.001) and HER-2 positive expression (P = 0.002)." (PMID 23351331, 2013). "Both the expression of GFRα1 and GFRα3 protein were significantly associated with tumor LNM (P = 0.001 and P = 0.006), higher clinical stage (P = 0.001 and P = 0.008) and HER-2 positive expression (P = 0.030 and P = 0.005) respectively." (PMID 23351331, 2013). "In the invasive margin, GFRA1 was identified as a pivotal molecule involved in cellular survival during liver metastasis formation, and we found that its oncogenic role depends on tumor associated macrophage (TAM)-derived GDNF." (PMID 36808605, 2023). "Furthermore, and consistent with our results, higher levels of GFRα1 mRNA were reported to be associated with tumor lymphovascular invasion and lymph node metastasis." (PMID 23351331, 2013). "This phenomenon suggests that for GC patients with a high GFRA1 expression in their tumor cells, the likelihood of liver metastasis is greater, but synergistic changes in the target organs are required." (PMID 36808605, 2023). "The GC data in the TCGA database show that the expression of GFRA1 gradually increases with tumor-node-metastasis (TNM) stage, with stage IV metastatic GC being highest, suggesting that its expression is closely related to the malignant progression of GC." (PMID 36808605, 2023). "Clusters of GFRA1+ cells were visible within the tumours and in tubules bordering the tumour regions (arrowheads)." (PMID 37564373, 2023). "In general, we conclude that during GC liver metastasis tumor cells express GFRA1 and are highly dependent on GDNF secreted by TAMs in the microenvironment at the invasive margin." (PMID 36808605, 2023). "Examples of receptors overexpressed in SCLCs included ERBB3 (tumor ligands NRG1, NRG2) and GDNF receptor 1 encoding GFRA1 (ligand NCAM1)." (PMID 36271074, 2022). "For example, circGFRA1 can promote tumor proliferation and inhibit apoptosis by binding to miR-34a and upregulating the expression of GFRA1 in TNBC." (PMID 33648498, 2021). "After that, we used 92 clinical patient samples (75 tumor tissues and 17 paracancerous tissues) to determine the degree of methylation upstream of GFRA1 TSS by time-of-flight mass spectrometry." (PMID 33175846, 2020). "The AUC values of the eight probe sequences ranged from 0.6 to 0.7, indicating that GFRA1-low methylation can be used as a methylation biomarker for tumor invasion." (PMID 33175846, 2020). "To further explore the relationship between GFRA1 methylation and tumor invasion, we performed a full-length methylation modification analysis of GFRA1 using 450K methylation chip data derived from TCGA." (PMID 33175846, 2020). "We demonstrate in this study that both APE1 and GFRα1 are markedly expressed in adenocarcinoma cells in comparison to normal cells, and their expression seems to be involved in tumor progression." (PMID 32438692, 2020). "In summary, our findings indicate that GFRA1 functions as a tumor promoting factor to promote CRC invasion through inducing EMT." (PMID 33175846, 2020). "IHC analysis revealed that GFRA1 is expressed on tumor-cell membranes not only in ER-positive breast cancers, as has been observed in previous studies, but also in 23% of TNBCs." (PMID 29796165, 2018).
tumor (continued). "As expected, we observed significant tumor growth inhibition and regression in models with strong GFRA1 expression." (PMID 29796165, 2018). "GFRA1-PBD demonstrated synthetic lethality with DDR deficiency, both in vitro in BRCA1-isogenic paired cells and in vivo in the CTG-0012 model, suggesting enhanced sensitivity of tumor cells to a GFRA1 ADC despite low receptor density." (PMID 29796165, 2018). "GFRA1-PBD showed evidence of tumor inhibition at a low dose of 0.3 mg/kg and induced significant tumor regression at the standard dose of 1 mg/kg." (PMID 29796165, 2018). "Although CTG-0012 displayed the lowest level of GFRA1 expression in the study, we still observed tumor regression at 1 mg/kg and tumor stasis at a lower dose of 0.3 mg/kg." (PMID 29796165, 2018). "Compared with vehicle control, GFRA1-PBD demonstrated the greatest tumor-growth inhibition in PDX models with strong GFRA1 staining, followed by those with moderate and weak staining." (PMID 29796165, 2018). "The association of tumor expression of ARTN and GFRα1 with the clinicopathological features of LSCC was then investigated." (PMID 25120606, 2014). "Targeting the GDNF/GFRα1 signalling axis could offer new avenues for treatment, aiming to inhibit tumour growth and improve patient outcomes." (PMID 40686838, 2025). "In addition, we found that the GFRA1 protein was mainly expressed on the surfaces of the tumor cells, and that GDNF was mainly expressed in stromal cells." (PMID 36808605, 2023). "The observation of GFRA1+ SPG clusters in tubules adjacent to tumours lead us to hypothesise that Inha KO tumours secrete factors that promote SSC self-renewal and maintenance." (PMID 37564373, 2023). "Therefore, the finding of GFRA1+ cell clusters in seminiferous tubules adjacent to tumour regions (termed here ‘TAT’, for tumour associated tubules) was intriguing." (PMID 37564373, 2023). "However, many questions about the role of GFRα1 signaling in tumor progression need to be studied and resolved." (PMID 35582425, 2022). "Tumors, via the expression of GFRα1, GFRα2, GFRα3, respond to molecules released by nerves and, in an autocrine fashion, to molecules released by the tumor itself and these interactions are likely amplified in the tumor microenvironment." (PMID 32252363, 2020). "Furthermore, we showed that this virus can mediate long-term GFRα1+ tumor regression upon intratumoral injection." (PMID 33233403, 2020). "Taken together, these data suggest that targeting GFRA1 could have an impact on different tumor subsets, with unique toxicity and activity profiles compared with RET." (PMID 29796165, 2018). "We further investigated whether tumor progression in these tumors is driven by the expression of GFRA1 and RET receptors or GDNF which is regulated in response to the inflammatory microenvironment surrounding many epithelial cancers." (PMID 29617307, 2018). "Thus, the identification of GFRA1 and other shared TAAs with favorable tumor: normal tissue expression profiles could create additional therapeutic options for TNBC." (PMID 29796165, 2018). "However, either deletion of GFRα-1 and/or nearby genes may contribute to the pathogenesis of these tumours." (PMID 10408842, 1999). "In conclusion, these results suggest that GFRA1, which is highly expressed in GC cells, relies on TAM-derived GDNF to promote tumor cells to resist apoptosis and to form liver metastases." (PMID 36808605, 2023). "Intriguingly, clusters of GFRA1+/EOMES+/LIN28A– cells, resembling a primitive SSC subset, were frequently observed in tubules adjacent to tumour regions." (PMID 37564373, 2023). "Glial cell derived neurotrophic factor receptor alpha 1 (GFRA1), a member of the GDNF ligand family, plays important roles in nervous system development, spermatogenesis and tumor progression." (PMID 33175846, 2020).
tumor (continued). "All of these results demonstrate that hypomethylation of GFRA1 promotes AKT phosphorylation and upregulates c-Jun expression, thereby, activating EMT to promote tumor invasion in CRC." (PMID 33175846, 2020). "DNA hypermethylation of the ADCY5, EVX1, GFRA1, PDE9A, and TBX20 genes resulted in reduced mRNA expression in tumorous tissue samples." (PMID 23544068, 2013). "We next determined if the worse survival outcome in patients with tumors with co-expression of either GFRα1 or GFRα3 and ARTN was restricted to tumor subtypes." (PMID 23351331, 2013). "GFRA1, interacting with glial cell-derived neurotrophic factor (GDNF), promotes tumor progression." (PMID 38962317, 2024). "In tumor xenografts, they showed that the inflammatory cytokines tumor necrosis factor-α and interleukin-1β act synergistically to up-regulate GDNF expression and this effect is mediated by a GDNF/GFRA1/RET axis." (PMID 29617307, 2018). "Because GFRA1 is a GPI-anchored protein, proteolytic cleavage could result in its shedding from the tumor cell surface." (PMID 29796165, 2018). "The safety profile of GFRA1-PBD was evaluated in a non-tumor-bearing non-GLP rat toxicity model." (PMID 29796165, 2018). "Reduced expression of the mRNAs for the ADCY5, EVX1, GFRA1 and PDE9A genes was significantly correlated with clinicopathological parameters, indicating that DNA methylation alterations, even from the precancerous stage, ultimately determine the tumor phenotype through gene silencing." (PMID 23544068, 2013). "For the HPV-negative cell lines, we had previously studied GDNF effect on SCC22A cells (HPV-negative with high GDNF/GFRα1 expression) and reported that high dose GDNF treatment did not affect SCC22A tumor growth or response to radiation." (PMID 32084217, 2020). "We describe GFRA1 as a TAA amenable to ADC targeting due to its internalization capacity, its highly specific expression in tumor-cell membranes, and its limited expression in essential normal tissues." (PMID 29796165, 2018).
infection (3 papers, 2018 to 2020). The state of being infected such as from the introduction of a foreign agent such as serum, vaccine, antigenic substance or organism. "In this report we demonstrate that HSV vectors can be completely retargeted for infection via GFRα1." (PMID 33233403, 2020). "We show that GFRα1 is necessary and sufficient for infection by the purified recombinant virus." (PMID 33233403, 2020). "At GFRA1-PBD doses up to 1.5 mg/kg, all animals survived until scheduled necropsy, with the exception of one animal from the 1.5–mg/kg-dose group that was sacrificed early because of infection related to severe myelosuppression." (PMID 29796165, 2018).
adenocarcinoma (2 papers, 2012 to 2020). A common cancer characterized by the presence of malignant glandular cells. "GDNF family receptor alpha 1 (GFR-alpha 1) and the receptor tyrosine kinase (RET) are involved in the pathophysiology of both the enteric nervous system and adenocarcinoma cells, suggesting their involvement in the pathology of polypoid GN." (PMID 22978818, 2012).
peripheral neuropathy (1 paper, 2018). A disorder affecting the peripheral nervous system. "Additionally, the selection of a DNA-targeting payload on the GFRA1 ADC may offer a mechanism to minimize the risk of peripheral neuropathy." (PMID 29796165, 2018).
psychiatric disorder (1 paper, 2011). A disorder characterized by behavioral and/or psychological abnormalities, often accompanied by physical symptoms. "The location of the strongest association signal within a gene of high potential relevance to psychiatric disorders (GFRA1) increases the probability that these findings may be true but modest signals of association." (PMID 21750702, 2011).
GFRA1 also shares sentences with these, for which no sentence is quoted: lung carcinoma (5 papers); ischemia (2); ovarian carcinoma (2); somatotroph adenomas (2); Stroke (2); Alzheimer disease (1); autism spectrum disorder (1); benign tumors (1); bipolar disorder (1); bone cancer (1); cognitive disorder (1); COVID-19 (1); deafness (1); hearing loss (1); hyperlipidemia (1); intestinal neuronal dysplasia (1); medullary thyroid carcinoma (1); microcephaly (1); mood disorder (1); neuroectodermal tumor (1); neurological disorders (1); neurotoxicity (1); Obstructive azoospermia (1); oral squamous cell carcinoma (1); osteoarthritis (1); osteomyelitis (1); papillary thyroid carcinoma (1); Parkinsonism (1); renal hypoplasia (1); spinal cord injury (1).
A further 3 diseases each share a sentence with GFRA1 in 1 paper.